MALAT1 (metastasis associated lung adenocarcinoma transcript 1)
Diseases named in the same sentence as MALAT1 in open-access papers (continued):
Sharing a sentence is not in itself a finding about the gene and the disease.
liver fibrosis (continued). "In KCs isolated from in vivo liver fibrosis model or in vitro M1-polarized macrophages, METTL3 was up-regulated, and sequentially, it increased MALAT1 level via m6A methylation, which promoted USP8 mRNA degradation through the interaction with PTBP1." (PMID 34839365, 2021). "MALAT1 and METTL3 expressions presented a time-dependent increase with the progression of CCL4-induced liver fibrosis." (PMID 34839365, 2021). "Collectively, these data suggest that MALAT1 is essential for activating M1 macrophages and NLRP3 inflammasome-mediated pyroptosis in CCl4-induced liver fibrosis." (PMID 34839365, 2021). "In the context of fibrosis, few examples showing their pro-fibrotic role have been documented, such as MALAT1 in cardiac fibrosis, H19 and DNM3os in lung fibrosis, and MALAT1, lnc-LFAR1 and HIF1A-AS1 in liver fibrosis." (PMID 31018516, 2019). "What’s more, MALAT1 is also reported that it acts as a competing endogenous RNA for miR-101b to regulate RAS-related C3 botulinum substrate 1 (Rac1) and contributes to hepatic fibrosis." (PMID 30534359, 2018). "Interestingly, an upregulation of MALAT1 was also observed in patients with NAFLD and was suggested to contribute to the progression of liver fibrosis." (PMID 40002783, 2025). "Notably, lncRNA-H19, -MALAT1, and -PVT1 are positively correlated with liver fibrosis, while lncRNA-P21 and -GAS5 are potential inhibitors of the liver fibrosis process." (PMID 39044218, 2024). "In addition, the METTL3/MALAT1/PTBP1/USP8/TAK1 axis in liver fibrosis promotes pyroptosis and macrophage M1 polarization, thereby exacerbating liver fibrosis progression." (PMID 37063421, 2023). "Likewise, in liver fibrosis models, METTL3 and MALAT1 were upregulated in Kupffer cells and macrophages cells." (PMID 37227534, 2023). "Besides, MALAT1 was upregulated in patients with NAFLD, contributing to the progression of liver fibrosis." (PMID 35769097, 2022). "It is also reported that MALAT1 acts as a ceRNA for miR-101b to regulate RAS-related C3 botulinum substrate 1 (Rac1), promoting proliferation, cell cycle progression, and HSC activation and contributing to hepatic fibrosis." (PMID 32326098, 2020). "Although several LncRNAs that could affect hepatic fibrosis were already reported including lnc LFAR1, p21, MALAT1, MEG3 and so on." (PMID 32943114, 2020). "Inhibition of lncRNAs (HIF1A-AS, Gm5091, and lincRNA-p21) and overexpression of lncRNAs (MALAT1, SCARNA10, Lnc-LFAR1, and HOTTIP) involved in the TGF-β signalling pathway could promote HSC activation and subsequently induce hepatic fibrosis." (PMID 32098245, 2020). "MALAT1 expression is upregulated and regulates sirtuin 1 (SIRT1) in liver fibrosis." (PMID 32098245, 2020). "Furthermore, small interfering RNA transfection (siRNA) in JS-1 cells in vitro confirmed that lncRNA-H19, -MALAT1, and -PVT1 promoted liver fibrosis, whereas lncRNA-P21 and -GAS5 had the opposite effect on key fibrotic molecules, including α- smooth muscle actin and collagen I expression." (PMID 39044218, 2024).
thyroid cancer (38 papers, 2018 to 2025). "LncRNAs also regulate the induction of angiogenesis, with MALAT1 in particular enhancing neovascularization by promoting FGF2 secretion from tumor-associated macrophages in thyroid cancer, which supported tumor growth and metastatic potential." (PMID 41154428, 2025). "Long non-coding RNA MALAT-1 (metastasis associated lung adenocarcinoma transcript 1) was recently found to be involved in the progression of thyroid cancer." (PMID 34209679, 2021). "The Metastasis-Associated Lung Adenocarcinoma Transcript 1 (MALAT1) is a lncRNA overexpressed in different forms of thyroid carcinoma and its repression in MTC-derived cell line negatively affected cell proliferation and invasion." (PMID 33114343, 2020). "In the present study, we aimed to explore the association between MALAT1 polymorphisms and thyroid cancer (TC) susceptibility, as well as potential biological function in TC." (PMID 31788131, 2019). "In thyroid cancer, Metastasis-Associated Lung Adenocarcinoma Transcript 1 (MALAT1) is upregulated in several subtypes such as papillary and follicular cancer and Homeobox transcript antisense RNA (HOTAIR) acts as an oncogene and correlates with metastasis and poor prognosis." (PMID 33030666, 2021). "Furthermore, MALAT1 could promote angiogenesis of thyroid cancer by regulating tumor-associated macrophage FGF2 protein secretion." (PMID 30988072, 2019). "Recent studies have shown that lncRNAs that interact with estrogen receptors, such as Metastasis-Associated Lung Adenocarcinoma Transcript 1 (MALAT1), and lncRNA-H19 (H19), are enhanced by estrogen receptors in lung and thyroid cancers." (PMID 38095719, 2024). "Then, IGF2BP2 was highly expressed in thyroid cancer, and MALAT1 was found to up-regulate IGF2BP2 and enhance MYC expression via m6A modification recognition by competitively binding to miR-204." (PMID 36281789, 2022). "LncRNA MALAT1 acts a oncogenic role in thyroid cancer by regulating the miR-204/IGF2BP2/m6A-MYC axis." (PMID 35676619, 2022). "A previous study reported that lncRNA MALAT1 (ENSG00000251562 of the TRLs signature) promotes tumor angiogenesis in thyroid cancer by regulating functions of macrophage in the TIME." (PMID 36159987, 2022). "In thyroid cancer, several lncRNAs, such as MALAT1, H19, BANCR, and HOTAIR have been identified as contributing factors to tumor development, and used as novel biomarkers for early diagnosis or treatment." (PMID 34404767, 2021). "In thyroid cancer, several lncRNAs, such as MALAT1, H19, BANCR, HOTAIR have been identified as contributing factors to the development of cancer." (PMID 34404767, 2021). "For example, a regulatory network modulated by MALAT1 in thyroid cancer has shown that this lncRNA acts as a competing endogenous RNA (ceRNA) by sequestering miR-204." (PMID 34445233, 2021). "LncRNA MALAT1 contributed to thyroid cancer progression through the upregulation of IGF2BP2 by binding to miR-204." (PMID 34917609, 2021). "The expression level of metastasis-associated lung adenocarcinoma transcript 1 (MALAT-1) and IQGAP1 are both increased in tissues of patients with thyroid cancer and thyroid cancer cells." (PMID 33996538, 2021). "Specifically, this study revealed that, in thyroid cancer, MALAT-1 and insulin-like growth factor 2 mRNA binding protein 2 (IGF2BP2), a member of RNA binding proteins, were expressed while mir-204 was expressed poorly." (PMID 34445233, 2021). "MALAT1 promotes thyroid cancer progression by binding to miR-204 and upregulating IGF2BP2, thereby affecting miR-204/IGF2BP2/m6A-MYC signaling." (PMID 34026852, 2021). "Studies have found that MALAT1 can promote the proliferation and metastasis of thyroid cancer cells." (PMID 32596158, 2020). "MALAT1 promotes the formation of blood vessels in thyroid cancer by regulating the secretion of the FGF2 protein in tumor-associated macrophages (TAMs), thereby promoting biological behaviors such as proliferation and metastasis in thyroid cancer cells." (PMID 32596158, 2020).
thyroid cancer (continued). "Huang and colleagues also confirmed the upregulation of MALAT1 in differentiated thyroid cancers in comparison with adjacent normal thyroid tissues." (PMID 32760219, 2020). "In addition, FGF2 can promote angiogenesis in thyroid cancer through the regulation of the lncRNA MALAT1." (PMID 38393692, 2024). "LncRNA-MALAT1 (metastasis-associated lung adenocarcinoma transcript 1) is highly expressed in TAMs and promotes the secretion of FGF2, thus promoting the proliferation, migration, and invasion of thyroid cancer cells." (PMID 38933287, 2023). "MALAT1 has already been investigated for its activity as an oncogene in various types of cancer, such as breast, endometrial, lung, gastric, ovarian, prostate, and thyroid cancer, along with other cancers." (PMID 38203269, 2023). "We defined a predictive algorithm based on naïve Bayes classifier for identifying patients with thyroid cancer with accuracy of 94.12% (sensitivity 100% and specificity 91.67%) using MALAT1, HOTAIR, and PVT1 expression in FNA samples and the cytological class." (PMID 33030666, 2021). "MALAT1 may play different roles in different thyroid tumors, and its effect is determined by the type of thyroid cancer." (PMID 32596158, 2020). "Put together, these results suggest that MALAT1 plays an essential role in the pathogenesis of thyroid cancers and may have a significant role in anaplastic thyroid CSCs." (PMID 32760219, 2020). "This study also found that MALAT1 expression levels in poorly differentiated thyroid carcinomas and anaplastic thyroid carcinomas are significantly lower than those in normal thyroid tissues, with expression in anaplastic thyroid carcinomas (ATCs) showing the lowest levels." (PMID 32596158, 2020). "This was the first report of MALAT1 being downregulated in any malignancy, and it indicates that MALAT1 may be a potential tool in classification of thyroid carcinoma." (PMID 32596158, 2020). "Regarding thyroid cancer, MALAT1 is highly expressed in PTC than in FTC and ATC." (PMID 31717449, 2019). "Upregulated MALAT-1 in TAMs isolated from thyroid cancer were able to skew macrophages towards M2 polarization, while the knockdown of MALAT-1 could promote macrophage repolarization from the M2 phenotype to the M1 phenotype and further inhibited thyroid cancer cell migration and invasion." (PMID 37637063, 2023). "Based on these results and on the observation that MALAT1 exhibited the higher expression in tumors and that HOTAIR and PVT1 the higher increase as compared to the contra-lateral tissue, we selected MALAT1, HOTAIR, and PVT1 as potential new diagnostic markers for thyroid cancer." (PMID 33030666, 2021). "There is a lack of in-depth information regarding the general role of lncRNAs in thyroid carcinoma since much of the research conducted to date has concentrated almost exclusively on a small group of well-characterized lncRNAs, such as HOTAIR and MALAT1." (PMID 40468332, 2025). "Sedaghati summarized the dysregulated and functional LncRNAs in thyroid cancer, including 28 upregulated LncRNAs, such as ANRIL, BANCR, H19, HOTAIR, MALAT1, and NEAT1, and 22 downregulated LncRNAs, including GAS5, NAMA, PTCSC2, and PTCSC3." (PMID 37874339, 2024). "LncRNA MALAT1 knockdown can inhibit tumor migration and invasion while increasing autophagy via miR-200a-3p/FOXA1 axis in thyroid cancer cells." (PMID 36880066, 2023). "LncRNA-MALAT1 knockdown in TAMs inhibits the propagation of thyroid cancer cells, and FGF2 overexpression rescues the inhibitory effects of MALAT1, indicating that lncRNA-MALAT1 exerts its role in an FGF2-dependent manner." (PMID 38933287, 2023). "More importantly, some non-coding RNAs were considered as the known prognosis biomarkers in thyroid cancer, such as let-7a, LINC-PINT, H19, MALAT1 and HOXA-AS2." (PMID 37153003, 2023). "Several lncRNAs, such as MALAT1, BANCR, and PTCSC3, have been identified to promote the proliferation and metastasis of thyroid cancers." (PMID 38298184, 2023).
thyroid cancer (continued). "High levels of expression of MALAT-1 and FGF2 were detected in M2-polarized THP-1 cells and TAMs (THP-1 cells stimulated by CM from thyroid cancer FTC133 cells) in vitro." (PMID 34209679, 2021). "MALAT-1-dependent FGF2 secretion by TAMs inhibited the secretion of pro-inflammatory cytokines, promoted proliferation, migration, and invasion of thyroid cancer cells and increased angiogenesis." (PMID 34209679, 2021). "In addition, Huang and colleagues indicated that the overexpression of MALAT1 and IQGAP1 is correlated with the proliferation and invasion of thyroid cancer cells." (PMID 32760219, 2020). "One study proposed that MALAT-1 overexpression could upregulate the expression of the IQ-domain GTPase-activating protein 1 (IQGAP1), thereby increasing the invasion of thyroid carcinoma cells." (PMID 29368602, 2018).
ischemic stroke (37 papers, 2018 to 2026). A stroke disorder caused by obstruction of blood flow to the brain, due to thrombotic (local blood clot formation) or embolic (due to a blood clot or other material traveling from another site) event. "Twelve lncRNAs were downregulated in ischemic stroke patients, with lncRNA metastasis-associated lung adenocarcinoma transcript-1 (MALAT1) being reported in more than one study." (PMID 39766887, 2024). "lncRNA,metastasis-associated lung adenocarcinoma transcript 1 (Malat1), has shown aregulatory role in the pathology of ischemic stroke." (PMID 38974129, 2023). "The anti-inflammatory lncRNA metastasis-associated lung adenocarcinoma transcript 1 (MALAT1) has been shown to be upregulated in microglia and neurons during ischemic stroke, resulting in enhanced sponging of the targeted miRNAs." (PMID 37550658, 2023). "An increase in MALAT1 expression has been associated with decreased susceptibility of the brain to ischemic stroke through the promotion of angiogenesis, inhibition of apoptosis, as well as inflammation and regulation of autophagy." (PMID 35053294, 2022). "For example, downregulation of the metastasis-associated lung adenocarcinoma transcript 1 (Malat1) lncRNA inhibits Beclin1-dependent autophagy by regulating miR-30a expression, thus reducing nerve cell death in ischemic stroke." (PMID 36420646, 2022). "In recent years, studies have shown that MALAT1 plays an important role in ischemic stroke in addition to being associated with a variety of cancers." (PMID 36275741, 2022). "Recent studies have demonstrated that MALAT1 was implicated in ischemic stroke." (PMID 33750458, 2021). "A growing number of studies have demonstrated that MALAT1 is associated with ischemic stroke, and could reduce the number of apoptotic neuronal cells, and inhibit autophagy by regulating microRNA miR-30 in cerebral ischemic stroke." (PMID 32138732, 2020). "It was found that a variation of the MALAT1 promoter, rs1194338 C > A, could be linked to ischemic stroke susceptibility." (PMID 33192490, 2020). "Therefore, we assessed the association between H19 and MALAT1 gene polymorphisms and susceptibility to ischemic stroke in a northern Chinese Han population." (PMID 30305120, 2018). "Among them, MALAT1, has been extensively studied for its role in ischemic stroke and MS pathogenesis, where it decreases OGD-induced apoptosis and regulates Th1/Th2 cell imbalances." (PMID 41602576, 2026). "Previous studies have established that MALAT1 promotes inflammation in ischemic stroke, as it is upregulated in neurons and microglia following hypoxia." (PMID 40869277, 2025). "Recent studies have identified several lncRNAs that modulate autophagy in ischemic stroke, including MALAT1, MIAT, SNHG12, H19, AC136007." (PMID 39021183, 2024). "Multiple studies reported differential expression of lncRNAs H19, GAS5, PVT1, TUG1, and MALAT1 in ischemic stroke." (PMID 39766887, 2024). "In ischemic stroke, some lncRNAs play the role of anti-inflammation and/or anti-apoptosis, such as MALAT1 and Nespas." (PMID 37187956, 2023). "Silencing of Malat1 in cerebral microvascular endothelial cells and ischemic stroke model mice resulted in increased expression of the pro-inflammatory cytokines CMP-1, IL-6, and E-selectin." (PMID 36420646, 2022). "At the same time, the up-regulation of MALAT1 can increase microvascular integrity in ischemic stroke." (PMID 35053294, 2022). "LncRNA Malat1 is involved in brain tissue damage induced by ischemia-reperfusion injury by affecting AQP4 expression via competitively binding miR-145 in ischemic stroke." (PMID 36420646, 2022). "Another study found that lncRNA MALAT1 showed a beneficial effect on ischemic stroke by mediating anti-apoptotic and anti-inflammatory responses." (PMID 36009062, 2022). "MALAT1 can regulate autophagy in ischemic stroke through sponging miRNA and regulating their effects on autophagy-related factors." (PMID 35053294, 2022).
ischemic stroke (continued). "Particularly in ischemic stroke (IS), the abnormal expression of MALAT1 played important roles including promotion of angiogenesis, inhibition of apoptosis and inflammation and regulation of autophagy." (PMID 32238151, 2020). "A previous study also indicated that MALAT1 promoted neuronal cell death and suppressed autophagy through targeting miR-30a in ischemic stroke." (PMID 33613191, 2020). "For example, lncRNA Malat1 protects brain tissues against ischemic stroke by binding to Bim and E-selectin." (PMID 30926681, 2019). "Silencing of MALAT1 increased cerebral vascular damage, worsened neurological and motor functions, and induced neuroinflammation in ischemic stroke." (PMID 29651234, 2018). "Although we have discovered some functional lncRNAs such as H19 and MALAT1 in ischemic stroke, however, the exploration of lncRNAs still faces multiple challenges." (PMID 29651234, 2018). "Since cerebral vasculature is important in improving clinical outcomes in the post-ischemic recovery phase, increasing MALAT1 in ischemic stroke suggested a protective and healing property of the ischemic brain." (PMID 29449542, 2018). "Both H19 and MALAT1 have complex regulatory mechanisms in ischemic stroke and evidences are emerging." (PMID 29651234, 2018). "This MALAT1-miR-26b-ULK2 regulatory axis involved in BMEC autophagy provides new insight into the ischemic stroke mechanisms." (PMID 29651234, 2018). "Notably, recent studies have revealed that berberine’s regulatory effect on HMGB1 is associated with lncRNA Malat1, where lncRNA Malat1 competitively binds miR-181c-5p - a direct HMGB1 target - to regulate HMGB1 expression following ischemic stroke." (PMID 40756985, 2025). "Furthermore, MALAT1 is known to be upregulated following ischemic stroke, where it promotes inflammation." (PMID 40869277, 2025). "LncRNA Malat1 has been reported to be upregulated and to promote ischemic stroke injury." (PMID 38180752, 2024). "Therefore, MALAT1 regulates autophagy during ischemic stroke through the MALAT1/miR-26b/ULK2, MALAT1/moR-200c-3p/SIRT1, and MALAT1/miR-30a/Beckin-1 axes." (PMID 39021183, 2024). "It is predicted that MALAT1 has protective and healing properties in ischemic stroke injury, and may become a biomarker for cerebrovascular disease treatment and prognosis." (PMID 36275741, 2022). "The expression of Malat1 was also found to be upregulated in ischemic stroke, while its downregulation was shown to improve the neurological deficit score and reduce neuronal apoptosis and the size of cerebral infarction by regulating miR-211-5p to in turn regulate the expression of COX-2." (PMID 35991562, 2022). "Further investigation suggested that lncRNA Malat1 could positively regulate the expression of aquaporin-4 (AQP4) by competitively binding miR-145 to mediate the damage of astrocytes during ischemic stroke." (PMID 35346266, 2022). "We and others show that lncRNA Malat1 is one of the most highly upregulated lncRNA and plays an essential role in the protection against cerebral microvascular endothelial pathophysiology during ischemic stroke." (PMID 35346266, 2022). "Another study showed that mice with lncRNA Malat1 KO presented larger brain infarct size and worse neurological scores, indicating that Malat1 plays critical protective roles in ischemic stroke via anti-apoptotic and anti-inflammatory effects in the brain microvasculature." (PMID 35991562, 2022). "Moreover, a recent study reported that the lncRNA Malat1 significantly increased in the blood of ischemic stroke patients compared with the level in normal controls." (PMID 35991562, 2022). "Finally, more extensive knowledge about underlying signal pathways and the accurate positioning of exosomal MALAT1 in the treatment of ischemic stroke is required in order to provide clinical guidance." (PMID 36009062, 2022).